ACVR2A (activin A receptor type 2A)
Diseases named in the same sentence as ACVR2A in open-access papers (continued):
Sharing a sentence is not in itself a finding about the gene and the disease.
adenoma (2 papers, 2015 to 2021). A neoplasm arising from the epithelium. "Among the most interesting driver genes identified in the present MSH3-deficient adenomas are ACVR2A and ARID2." (PMID 34843512, 2021). "In addition, the MSH3-deficient adenomas harboured one to five (recurrent) somatic variants in 13 established or candidate driver genes for early colorectal carcinogenesis, including ACVR2A and ARID genes." (PMID 34843512, 2021). "Consistent with this, ACVR2A is regarded as a driver gene in MSI colorectal adenomas and is—after TGFBR2—the gene with the second highest rate of frameshift variants in MSI adenomas." (PMID 34843512, 2021). "Such analyses identified three genes (ACVR2A, TGFBR2, and SLC22A9) and an additional two genes (TCERG1 and TRIM59) whose mutations were enriched for clonal and adenoma-specific categories, respectively." (PMID 26336987, 2015). "Interestingly, variants in ACVR2A and in the ARID genes occurred in 7/9 adenomas." (PMID 34843512, 2021). "Besides established driver genes of colorectal tumourigenesis, our data suggest that ACVR2A and the ARID genes in particular are important targets in terms of adenoma formation." (PMID 34843512, 2021).
atherosclerosis (2 papers, 2019 to 2021). A disease characterized by the build-up of fatty material and calcium deposition in the arterial wall resulting in partial or complete occlusion of the arterial lumen. "Bone morphogenetic proteins receptor Acvr2a was reported to induce osteogenic differentiation and MC infiltration in atherosclerosis." (PMID 34987524, 2021).
Azoospermia (2 papers, 2020 to 2022). Absence of any measurable level of sperm,whereby spermatozoa cannot be observed even after centrifugation of the semen pellet. "Some target genes of the downregulated miRNAs, such as ACVR2A, CCND1, CCNE2, HMGA2, BMI1, NR2C2 and BCL2, have been associated with gonadal development, and germ cell maintenance through different pathways which could be relevant to the molecular mechanisms affected in KS patients with azoospermia." (PMID 32651451, 2020).
colitis (2 papers, 2015 to 2024). Inflammation of the colon. "The circRNA/miRNA/mRNA competitive endogenous RNA (ceRNA) network analysis showed that the candidate miRNAs were connected to well-known colitis-associated CRC ACVR2A, SOCS1, IGF2BP1, FAM126A, and CCDC85C mRNAs, and circ-SHPRH circRNA." (PMID 38891888, 2024).
liver disease (2 papers, 2022 to 2025). "It was observed that AR, CREB1, ACVR2A, and CXCL12 were down-regulated in T1DM-associated liver disease; however, they exhibited up-regulation after NAC treatment." (PMID 40001479, 2025).
Lynch syndrome (2 papers, 2008 to 2021). An autosomal dominant hereditary neoplastic syndrome characterized by the development of colorectal carcinoma and a high risk of developing endometrial carcinoma, gastric carcinoma, ovarian carcinoma, renal pelvis carcinoma, and small intestinal carcinoma. "Since it harbours coding microsatellites similar to TGFBR2, ACVR2A is one of the most frequently mutated genes in CRC in patients with Lynch syndrome and perturbation of TGFß signalling through truncating variants in ACVR2A is suggested to be an early event in CRC carcinogenesis." (PMID 34843512, 2021).
multiple sclerosis (2 papers, 2017 to 2018). A progressive autoimmune disorder affecting the central nervous system resulting in demyelination. "Indeed, regions that were actively myelinating (in perinatal tissue) or remyelinating (in multiple sclerosis lesions) demonstrated relatively higher densities of oligodendroglial lineage cells expressing Acvr2a compared to those expressing Acvr2b." (PMID 29397421, 2018). "In actively myelinating or remyelinating areas of human perinatal brain injury and multiple sclerosis tissue, respectively, oligodendrocyte lineage cells expressing Acvr2a outnumbered those expressing Acvr2b, whereas in non-repairing lesions Acvr2b+ cells were increased." (PMID 29397421, 2018).
Atrophy (1 paper, 2021). Any weakening or degeneration, especially through lack of use. "Parallel with in vitro results, T-MSC exosomes significantly downregulated ACVR2A and ACVR1B in Bu-Cy mice, possibly explaining how atrophy genes are attenuated by T-MSC exosomes." (PMID 34440938, 2021).
autoimmune disease (1 paper, 2019). A disorder resulting from loss of function or tissue destruction of an organ or multiple organs, arising from humoral or cellular immune responses of the individual to their own tissue constituents. "ACVR2A thus play a critical role in autoimmune disease progression and could be evaluated for common therapeutic purpose." (PMID 31554915, 2019).
breast tumours (1 paper, 2023). "ACVR1C, TGFBR2, TGFBR3, ACVR2A, ACVR1, BMPR1A and BMPR2 were lower in breast tumours while ACVR1B and BMPR1B exhibited relatively higher expression levels in paired tumours compared with normal breast tissues, in the TCGA_BRCA cohort." (PMID 37333824, 2023).
chondrosarcoma (1 paper, 2023). A malignant cartilaginous matrix-producing mesenchymal neoplasm arising from the bone and soft tissue. "Caution is warranted since i) FN1 and ACVR2A rearrangements in SC are reportedly present in only 57% of cases, and ii) these rearrangements were reported in 75% of cases with chondrosarcoma secondary to SC." (PMID 38179177, 2023).
Cirrhosis (1 paper, 2022). A chronic disorder of the liver in which liver tissue becomes scarred and is partially replaced by regenerative nodules and fibrotic tissue resulting in loss of liver function. "Genome‐wide association study (GWAS) summary statistics were extracted from seven studies (>1.7 million participants) for variants near ACVR2A, ALB, CIDEB, FOXO1, GPAM, NEAT1 and TNRC6B for: aminotransferases, liver fat, HbA1c, diagnosis of NAFLD, ARLD and cirrhosis." (PMID 35474605, 2022).
cyclopia (1 paper, 2023). "In one unique case, a gene (Acvr2a) was associated with cyclopia in addition to MAC anomalies confirming human findings in holoprosencephaly cases." (PMID 36737727, 2023). "As such, our study provided a mouse correlate for a holoprosencephaly-suspected gene from a case report, ACVR2, with cyclopia observed in Acvr2a−/− E15.5 embryos confirming the phenotype." (PMID 36737727, 2023).
endometrial tumors (1 paper, 2023). "This could help guide future targeted therapies, given the prevalence of ACVR2A K437 frameshift mutations in endometrial tumors." (PMID 36906706, 2023).
HELLP syndrome (1 paper, 2013). A life-threatening condition that can potentially complicate pregnancy. "Secondly, the genes identified by genome-wide linkage studies to be associated with pre-eclampsia (ACVR2A, STOX1) and the HELLP-syndrome (LINC-HELLP) are discussed regarding their potential functions in the etiology of disease." (PMID 24058367, 2013).
Infertility (1 paper, 2021). "To rule out any potential embryonic contribution to the infertility phenotype of the Smad1/5 cKO and Acvr2a cKO mutant mice, we also transferred embryos derived from Smad1/5 cKO and Acvr2a cKO donors to the uteri of WT recipients." (PMID 34099644, 2021).
infiltrating urothelial bladder carcinoma (1 paper, 2020). "GLI1 showed a significant level of co-expression in mucinous breast carcinoma and ovarian serous surface papillary carcinoma, whereas AMHR2, CHRD, and ACVR2A showed a similar pattern in ovarian serous papillary carcinoma, superficial bladder carcinoma and infiltrating urothelial bladder carcinoma." (PMID 31973134, 2020).
melanoma (1 paper, 2019). A malignant, usually aggressive tumor composed of atypical, neoplastic melanocytes. "Our qPCR results showed significant down-regulation of PAX9, NDRG2, and ACVR2a in melanoma compared with normal, and the relative expression of the respective miRNA–mRNA pairs showed significant negative correlation." (PMID 31569419, 2019). "ACVR2A is reported here for the first time in melanoma with significant negative correlation with miR-223." (PMID 31569419, 2019).
metastasis (1 paper, 2022). The spread or migration of cancer cells from one part of the body (where they first appeared) to another. "In addition, ACVR2A, ID1, and ID4 are enriched in the TGF-β signaling pathway, and the role of TGF-β in osteolytic bone metastasis was well known." (PMID 35063044, 2022).
nonalcoholic steatohepatitis (1 paper, 2024). "A recent study found higher mutation rates in the gene encoding activin A receptor type 2A among patients with nonalcoholic steatohepatitis (NASH)-associated HCC than among patients with HCC due to other etiologies (10% vs. 3%, p<0.05)." (PMID 38489301, 2024).
rheumatic diseases (1 paper, 2023). "Contrary to our findings, ACVR2A expression was reported to be elevated in rheumatic diseases; however, conclusions were drawn from a small sample size of 60 patients." (PMID 36928613, 2023).
small-bowel adenocarcinoma (1 paper, 2020). "In small-bowel adenocarcinoma, exome-wide somatic mutation characterization identified acvr1b and acvr2a as novel candidate driver genes." (PMID 32066878, 2020).
uterine tumors (1 paper, 2023). "We profiled the data from uterine tumors deposited to the cBioPortal of Cancer Genomics for mutations of the TGFβ signaling pathway and identified several mutations in TGFβ-related receptors (TGFBR1, TGFBR2, ACVR1B, ACVR1C, ACVR2A, ACVR2B) and transcription factors (SMAD2, SMAD3, SMAD4)." (PMID 36906706, 2023).
tumor (59 papers, 2006 to 2025). "Lastly, transcriptomic datasets and scRNA-seq have inherent technical limitations in capturing the tumor microenvironment of ACVR2A-deficient HCC." (PMID 40139191, 2025). "In DSS tumors, activin signaling genes (Acvr1b, Acvr2a, and Smad4) were highly mutated, suggesting the involvement of activin signaling in inflammation-associated tumor development." (PMID 37845228, 2023). "ACVR2A, which encodes activin receptor type IIA, is a component of the TGFβ signaling pathway, shown to function as a tumor suppressor gene in human CRC-derived organoids." (PMID 34198908, 2021). "ACVR2A is a member of the transforming growth factor beta superfamily that plays a role in pathways associated with tumor progression and suppression." (PMID 32754579, 2020). "In MSI tumours, the most frequently mutated known cancer genes were ACVR2A (9/9, 100%), MSH3 (5/9, 56%), FBXW7 (5/9, 56%), and BRAF (5/9, 56%)." (PMID 30894686, 2019). "Consistent with this we also identify alterations in the ACVR2A gene that encodes for an activin/BMP receptor enriched in this tumour group, which is also downregulated during tumour progression implying a tumour suppressor role for this gene." (PMID 30202019, 2018). "The sister’s tumor had one PV in ACVR2A, the most frequently mutated gene in MSI AYA-CRCs." (PMID 36291559, 2022). "We also revealed the biological effects of Acvr2a KO on the tumorigenic ability, tumor immune microenvironment, and intratumoral lactate levels using 3H3-Pten-KO cells." (PMID 40139191, 2025). "VB124 monotherapy exerted suppressive effects on tumor tissues derived from the Hepa1-6 KO cells and 3H3-Pten-KO cells with Acvr2a KO, and its combination with anti-PD-1 antibody significantly enhanced the anti-tumor response." (PMID 40139191, 2025). "Here we present new humanized isogenic models for G3MB driven by MYC amplification and overexpression of TGFβ pathway effectors ACVR2A, TGFβR1, and TGFβ1 that recapitulate the human tumor type." (PMID 41415380, 2025). "We proceeded to evaluate the tumorigenic property and tumor immune microenvironment of ACVR2A-KO cells." (PMID 40139191, 2025). "In the tumor tissues of Hepa1-6 cells with Acvr2a KO and Ldha KD, the number of infiltrating CD8+ T cells was increased, while the number of Foxp-3+ Treg cells was decreased." (PMID 40139191, 2025). "To examine the anti-tumor potential of lactate control on ACVR2A-KO tumors, we first established HuH7 KO and Hepa1-6 KO cells with tetracycline-inducible shMCT4." (PMID 40139191, 2025). "Subsequently, we explored ACVR2A’s influence on CRC advancement through in vivo tumor experiments and hematoxylin–eosin (HE) staining." (PMID 38898042, 2024). "Hematoxylin–eosin (HE) staining demonstrated a significant increase in tumor area in the ACVR2A-inhibitor group and a decrease in the ACVR2A-mimic group compared to the NC group." (PMID 38898042, 2024). "In the BRAF and RNF43 tumours, co-occurring mutations were observed in ACVR2A (FDR-adjusted P = 0.06) in HM tumours, and AKT1 (FDR-adjusted P = 0.03) and TYRO3 (FDR-adjusted P = 0.08) in the nHM tumours." (PMID 39112715, 2024). "Seven heterozygous protein-truncating mutations were found in tumor suppressor genes including RB1, FBXO11, FAT1, KMT2D, KMD6A, ACVR2A and ZFHX3." (PMID 36702998, 2023). "Seven of the 64 tumour suppressors (ACVR2A, CSMD3, EPS15, MAP2K4, NF1, PBRM1 and RB1) had intronic mis-splicing mutations in multiple tissues." (PMID 33420369, 2021). "Five tumor suppressor genes have variants (RNF43 G659fs, NPM1 W288fs, RPL22 K15fs, ACVR2A K437fs, LARP4B T163fs) that occur in over 5% of samples in at least one cohort." (PMID 34214079, 2021).
tumor (continued). "The correlation with the level of ACVR2A expression andclinical stage was also determined according to the TNM classification andhistological grade of the tumor (G)." (PMID 30856244, 2019). "The most recurrent frameshift MSI events are found in ACVR2A (51.6% of the tumours), KIAA2018 (51%), SLC22A9 (50%), ASTE1 (45%), TGFBR2 (44%), NDUFC2 (36%), LTN1 (36%) and SEC31A (36%)." (PMID 28585546, 2017). "We found that 59/61 (97%) of MSI tumours had both TGFBR2 and ACVR2A insertion/deletion (indel) mutations in homopolymer regions of the targeted genes." (PMID 27302369, 2016). "The subcutaneous tumor xenograft experiment revealed that, relative to the negative control (NC) group, tumor volume markedly escalated in the ACVR2A-inhibitor group but substantially diminished in the ACVR2A-mimic group." (PMID 38898042, 2024). "It seemed that ACVR2A, FANCA, RBM10, and SPTA1 mutations might have important functions in tumour development for different subtypes and different molecular characteristics in Chinese patients." (PMID 38024139, 2023). "Additionally, ACVR2A expression was similar between normal pancreas and tumor, whereas ACVR2B was downregulated in the tumors." (PMID 37083240, 2023). "The gene cluster (LRP1, ACVR2A, and SETBP1) could be a good biomarker of these patients with a family risk, which was characterized by right-sidedness, high tumor mutational burden, and high microsatellite instability." (PMID 35814400, 2022). "However, in PDAC alterations of TGFβ signaling through the mutation of genes involved in the pathway (e.g., SMAD4, SMAD3, TβR-I, TβR-II, ACVR1B, and ACVR2A), this role is present in 47% of cases, highlighting that TGFβ can sometimes acts as a tumor promoter." (PMID 32429474, 2020). "ACVR2A is believed to be a tumor suppressor that inhibits the growth anddifferentiation of cells." (PMID 30856244, 2019). "The ACVR2A gene expression level was compared with severalclinicopathological parameters, such as the size and depth of primary tumor invasion(T), the presence of metastases in the regional lymph nodes (N), and the presence ofdistant metastases (M) according to the TNM classification." (PMID 30856244, 2019). "There was no statisticallysignificant association between ACVR2A gene expression and age,gender, histological type, grading of tumor, vascular invasion, and presence oflymphocytes in tumor tissue." (PMID 30856244, 2019). "In three of these pairs the tumours shared the same driver mutation either in BRAF, APC, or ACVR2A." (PMID 30894686, 2019). "An increase of p21 and a decrease in pAKT in the tumor tissue of ACVR2A KO mice is significant." (PMID 26497569, 2015). "Crucially, ACVR2A may act as a tumor suppressor in CRC, impeding tumorigenesis and differentiation." (PMID 38898042, 2024). "To determine whether tumor cell activin receptor signaling is important in enzalutamide resistance in vivo, we generated MycCaP-Bo cells expressing doxycycline-inducible shRNA targeting Acvr1b and Acvr2a, respectively." (PMID 36749798, 2023). "The assessment of ACVR2A mRNA expression levels across multiple cell lines revealed that HTR8/SVneo and JAR cells exhibited comparable levels to tumor cells such as A549, suggesting a potential role for ACVR2A in trophoblast cell functions." (PMID 40444773, 2025). "Protein kinases such as ACVR2A and PRKACA participate in signaling pathways governing cell growth and differentiation, with their dysregulation contributing to tumor progression." (PMID 39273340, 2024). "The size of the tumor also affected the expression of BMP3 (P = 0.0047), BMP7 (P = 0.0210), BMPR1B (P = 0.0460), ACVR2A (P = 0.0350), ACVRL1 (P = 0.0045), TGFBR2 (P = 0.0170), and TGFBR3 (P = 0.0150) according to the K-W test." (PMID 34036102, 2021). "Undercoverage of several genes (ACVR2A, ASTE1, KIAA2018, SLC22A9, and TGFBR2) were common events across multiple tumor types, including STAD." (PMID 30281678, 2018).